SYT8 (synaptotagmin 8)
Description:
Involved in the trafficking and exocytosis of secretory vesicles in non-neuronal tissues. Mediates Ca(2+)-regulation of exocytosis acrosomal reaction in sperm. May mediate Ca(2+)-regulation of exocytosis in insulin secreted cells.
Synonyms: DKFZp434K0322
Tractability: Antibody: UniProt places it where antibodies can reach, with medium confidence; UniProt predicts a signal peptide or a membrane-spanning region; its Gene Ontology location is reachable by antibodies, with medium confidence.
Gene: Protein-coding gene on chromosome 11 (1,828,307 to 1,837,521, forward strand). Ensembl gene ENSG00000149043.
Subcellular location: Cell membrane; Cytoplasmic vesicle, secretory vesicle, acrosome
Subcellular location (Human Protein Atlas): Endoplasmic reticulum; Nucleoli fibrillar center
Pathways (Reactome):
Vesicle-mediated transport: Cargo recognition for clathrin-mediated endocytosis; Clathrin-mediated endocytosis
Gene Ontology:
Molecular function: calcium ion sensor activity; calcium-dependent phospholipid binding; SNARE binding; calcium-dependent protein binding
Biological process: calcium-dependent activation of synaptic vesicle fusion; regulation of calcium ion-dependent exocytosis; regulation of synaptic vesicle exocytosis; vesicle-mediated transport; acrosome reaction
Cellular component: axon; dense core granule; exocytic vesicle; plasma membrane; synaptic vesicle membrane; acrosomal vesicle; cytoplasm; membrane; vesicle
Genetic constraint (gnomAD): Loss-of-function variants: 50 observed, 34.1 expected, observed/expected ratio (o/e) 1.47, 90% interval 1.17 to 1.83. The upper end of that interval is the gene's LOEUF score, 1.83, which puts it in group 6 of 6, group 1 being the genes least tolerant of losing a copy. Missense variants: 595 observed, 493.44 expected, observed/expected ratio (o/e) 1.21, 90% interval 1.13 to 1.29. Synonymous variants: 255 observed, 218.52 expected, observed/expected ratio (o/e) 1.17, 90% interval 1.05 to 1.29.
Homologues: Orthologues: chimpanzee SYT8 (97% identical), macaque SYT8 (78% identical), dog SYT8 (75% identical), mouse Syt8 (75% identical), rat Syt8 (74% identical), pig SYT8 (70% identical), guinea pig SYT8 (67% identical), tropical clawed frog syt8 (45% identical). Paralogues in human: SYT1 (40% identical), SYT5 (39% identical), SYT2 (39% identical), SYT6 (30% identical), SYT10 (30% identical), SYT9 (29% identical), SYT3 (28% identical), SYT11 (26% identical), SYT17 (26% identical), SYT4 (26% identical), SYT12 (25% identical), SYT7 (25% identical), and 19 more.
Diseases named in the same sentence as SYT8 in open-access papers:
SYT8 is named in the same sentence as 8 diseases in open-access papers, as found by Europe PMC text mining. Sharing a sentence is not in itself a finding about the gene and the disease. The quoted sentences say what the papers report.
gastric cancer (6 papers, 2018 to 2024). A primary or metastatic malignant neoplasm involving the stomach. "In gastric cancer, SYT8 expression is associated with increased peritoneal metastasis and can potentially serve as a diagnostic and prognostic marker." (PMID 34907162, 2021). "Because SYT8 has been reported to favor tumor invasion and metastasis in gastric cancer, we next sought to determine the role of SYT8 in altering tumor characteristics in pancreatic cancer cell lines." (PMID 34907162, 2021). "Also, the expression levels of synaptotagmin VIII (SYT8) were higher in gastric cancer tissues of patients with peritoneal recurrence or metastasis." (PMID 38596287, 2024). "The distinct roles of SYT8 and MAGED2 in the progression of gastric cancer synergistically enhanced predictive performance, achieving stratification that is more precise." (PMID 29733517, 2018). "The four constituents of the expression panel, MAGED2, SYT8, BTG1, and FAM46, have individual roles in gastric cancer progression." (PMID 29721160, 2018).
pancreatic cancer (4 papers, 2021 to 2023). "Along with the orphan nuclear receptor ERRα, Tnni2 was identified as a crucial protein contributing to increased cell proliferation, migration and invasion of pancreatic cancer by up-regulation of Sirt1 and downstream Syt8." (PMID 36077344, 2022). "SYT8 was overexpressed in tumor tissues of pancreatic cancer and played important roles in promoting cell proliferation, invasion, and migration both in vivo and in vitro." (PMID 36004367, 2022). "We observed an increase in SYT8 expression in pancreatic cancer patient tissues and in vitro cell lines." (PMID 34907162, 2021). "All pancreatic cancer cell lines showed a significantly higher increase in SYT8 mRNA and protein expression levels when compared to HPDE cells." (PMID 34907162, 2021). "Our study identifies SYT8 as a potential prognostic marker of pancreatic cancer and provides a deeper mechanistic understanding of pancreatic cancer progression." (PMID 34907162, 2021). "Taken together, these results suggested that SYT8 directly regulates cell survival and tumor growth in pancreatic cancer." (PMID 34907162, 2021). "In the present study, we characterized the role of the synaptic protein, SYT8, in the progression of pancreatic cancer." (PMID 34907162, 2021). "Further studies are required to determine whether other ERRα interactors are also involved in the regulation of SYT8-mediated pancreatic cancer progression." (PMID 34907162, 2021). "In the present study, we used pancreatic cancer cell lines in vitro, an in vivo tumor mouse model, and pancreatic cancer patient tissue samples to identify a novel SYT8-dependent molecular mechanism mediating pancreatic cancer cell proliferation and invasion via TNNI2, ERRα, and SIRT1." (PMID 34907162, 2021). "We showed that SYT8 was capable of altering the expression levels of key factors that regulate cell metabolism, to promote cell proliferation and invasion in the context of pancreatic cancer." (PMID 34907162, 2021). "In this study, we identified a previously unknown role of SYT8 in altering tumor characteristics in pancreatic cancer." (PMID 34907162, 2021). "We further quantified mRNA expression levels of SYT8 in 30 pairs of pancreatic tumor and healthy tissues from patients by quantitative reverse transcription polymerase chain reaction (qRT-PCR) and observed a moderate but significant increase in SYT8 expression." (PMID 34907162, 2021). "Thus, we speculated that the TNNI2/ERRα axis was involved in SYT8-mediated pancreatic cancer progression." (PMID 34907162, 2021). "Finally, it may be concluded that SYT8 may serve as an oncogene in pancreatic cancer and GC." (PMID 36004367, 2022). "However, there is no clear understanding of how SYT8 promotes metastasis in pancreatic cancer." (PMID 34907162, 2021).
depression (2 papers, 2024 to 2025). "SYT8 rs3741231 G allele and SSPO rs12536873 TT genotype are associated with both IBS and depression, which of these variants are important in neurogenesis and neurotransmission." (PMID 40755502, 2025).
pancreatic duct adenocarcinoma (1 paper, 2021). "To investigate the effects of SYT8 in the context of pancreatic duct adenocarcinoma, we analyzed 179 patient tumor tissues and 171 non-tumor tissues for expression of SYT8 using the Gene Expression Profiling Interactive Analysis (GEPIA) platform." (PMID 34907162, 2021).
psoriasis (1 paper, 2017). An autoimmune condition characterized by red, well-delineated plaques with silvery scales that are usually on the extensor surfaces and scalp. "Notably, some genes strongly decreased in psoriasis lesions were elevated by IMQ in most strains (Syt8, Cdhr1, Cntn2)." (PMID 28279190, 2017).
tumor (3 papers, 2021 to 2023). "Together, we identified SYT8 to be a central regulator of tumor progression involving signaling via the SIRT1, ERRα, and TNNI2 axis." (PMID 34907162, 2021). "In summary, our results indicated that SYT8 plays an important role in both promoting cell invasion in vitro and tumor metastasis in vivo." (PMID 34907162, 2021). "To identify the mechanism behind SYT8-mediated regulation of tumor metastasis, we investigated the role of SIRT1, a protein deacetylase that plays a wide role in regulating the cell cycle during apoptosis." (PMID 34907162, 2021). "In addition to our in vitro and in vivo tumor growth studies, we also performed an in vivo metastasis assay, which further confirmed that SYT8 expression was a significant driver of tumor metastasis as observed in most late-stage pancreatic patients." (PMID 34907162, 2021). "Increased SYT8 expression also promoted tumor metastasis in an in vivo tumor metastasis model." (PMID 34907162, 2021). "However, in recent years, several studies have shown that abnormal expression of SYT8 may affect the occurrence and development of tumor diseases." (PMID 36004367, 2022). "T-C2 comprised one-fourth of the tumor section and showed relatively high expression of TNNI2 (troponin I2, a fast-twitch skeletal muscle protein) and SYT8 (synaptotagmin 8 and a membrane protein that is important in neurotransmission and hormone secretion), which have been found to promote PC." (PMID 37124494, 2023). "This analysis revealed that SYT8 levels were significantly higher in tumor tissues when compared with non-tumor healthy tissues." (PMID 34907162, 2021). "Furthermore, when siSYT8-expressing or SYT8-overexpressing BxPC-3 or PANC-1 cells were transferred to BALB/c nude mice and monitored for tumor growth, we observed a significant decrease in tumor size over 6 weeks in the siSYT8-expressing mice compared to an increase in the SYT8 overexpression group." (PMID 34907162, 2021).
cancer (1 paper, 2021). A tumor composed of atypical neoplastic, often pleomorphic cells that invade other tissues. "To further gain insight into the mechanism by which SYT8 and SIRT1 mediated cancer progression, we investigated the orphan NR, ERRα, which was identified as a SIRT1 interactor by bioinformatics analysis." (PMID 34907162, 2021). "While the roles of SYT8 and TNNI2 have not been broadly described in the context of cancer, their expression levels have been shown to be increased in gastric and bladder-related cancers, indicating that SYT8 and TNNI2 could act as prognostic markers." (PMID 34907162, 2021).
SYT8 also shares sentences with these, for which no sentence is quoted: lymph node metastasis (1 paper).